CLU (clusterin)
Diseases named in the same sentence as CLU in open-access papers (continued):
Sharing a sentence is not in itself a finding about the gene and the disease.
bladder cancer (10 papers, 2011 to 2024). "The potential of alpha-2-macroglobulin (A2M) and clusterin (CLU) as novel diagnostic urinary EV (uEV) biomarkers for bladder cancer (BC) was demonstrated previously." (PMID 37676879, 2023). "Our previous study demonstrated the potential of alpha-2-macroglobulin (A2M) and clusterin (CLU) as novel diagnostic uEV biomarkers for bladder cancer (BC) through a comparative analysis of uEVs acquired from patients with BC before and after surgery using an antibody array." (PMID 37676879, 2023). "For instance, metformin was applied to target clusterin and inhibit lipid synthesis and the proliferation of bladder cancer cells via FASN." (PMID 39645039, 2024). "For example, our group innovatively demonstrated that metformin targeted Clusterin to regulate lipogenesis and inhibit the growth of bladder cancer cells through SREBP‐1c/FASN axis." (PMID 36052760, 2022). "Fb, LDHB, Apo-A1 and CLU showed increasing trend in urine samples of patients with bladder cancer, compared with healthy control, while Hp expression didn't change significantly." (PMID 21496341, 2011). "Another phase II preoperative randomized controlled trial involving patients with bladder cancer showed EGCG-rich green tea extract significantly reduced biological markers of bladder cancer tissue, including PCNA and clusterin, which are associated with tumor proliferation, invasion, and migration." (PMID 37292151, 2023). "We observed increased expression of five proteins, including fibrinogen (Fb), lactate dehydrogenase B (LDHB), apolipoprotein-A1 (Apo-A1), clusterin (CLU) and haptoglobin (Hp), which were increased in urine samples of patients with low malignant or aggressive bladder cancer." (PMID 21496341, 2011).
cerebral amyloid angiopathy (10 papers, 2017 to 2025). "Clusterin, also known as apolipoprotein J, is a diversely functioning glycoprotein that has been implicated in the development of many diseases, ranging from cerebral amyloid angiopathy to cancer." (PMID 38892036, 2024). "Immunocytochemistry and quantitative analysis revealed that intraventricular (icv) administration of clusterin peptide in Tg6799 mouse reduced Aβ plaques as well the severity of cerebral amyloid angiopathy." (PMID 29370749, 2018). "It was found that both APOE and CLU could delay the initiation time of amyloid growth kinetics in a concentration-dependent manner, acting as extracellular chaperones to inhibit amyloid-β deposition in patients with sporadic cerebral amyloid angiopathy." (PMID 33521130, 2021). "Consistently, peripheral administration of human recombinant apoJ/clusterin in APP23 mice, induced a reduction of insoluble Aβ and cerebral amyloid angiopathy in the brain." (PMID 33287338, 2020).
COVID-19 (10 papers, 2020 to 2025). A disease caused by infection with severe acute respiratory syndrome coronavirus 2. "We observed that certain genes in the severe COVID-19 gene set, such as IFI27, HLA-DQB1, and CLU, also hold significance in the context of influenza patient classification." (PMID 39350339, 2024). "Using this approach, genes S100A8, IFI27, CLU, IFITM3, and MT-CO1 have been identified as the stable gene panel for the classification of severe COVID-19 patients, utilizing the same training dataset as previously employed." (PMID 39350339, 2024). "Similarly, we find enrichment of several markers of pulmonary fibrosis (CLU, COL1A1, COL1A2, and COL3A1) in SARS-CoV-2-low samples as compared with nonviral and viral ARDS samples, exemplifying the profound lung injury and fibrosis during later stages of COVID-19." (PMID 35233546, 2022).
lung adenocarcinoma (10 papers, 2011 to 2023). A carcinoma that arises from the lung and is characterized by the presence of malignant glandular epithelial cells. "In conclusion, ITGAM and CLU were identified as serum exosomal protein markers of lung adenocarcinoma." (PMID 35291954, 2022). "We used WB to validate the differential expression of serum exosomal ITGAM and CLU among the advanced lung adenocarcinoma group, early lung adenocarcinoma group, and healthy control group." (PMID 35291954, 2022). "Our excitement was stimulated when we discovered that serum CLU expression in advanced lung adenocarcinoma was significantly higher than that in early lung adenocarcinoma and healthy controls, and the overexpression trend was stable." (PMID 35291954, 2022). "We detected the expression of CLU in the exosomes of patients with lung adenocarcinoma for the first time." (PMID 35291954, 2022). "In our study, CLU is overexpressed in cultured medium and serum samples in lung adenocarcinoma cells." (PMID 29296216, 2017). "We confirmed that CLSTN1, CLU and NGAL were potential serological biomarker for lung adenocarcinoma prognostic and diagnostic." (PMID 29296216, 2017). "In conclusion, we demonstrate that clusterin can influence transdifferentiation from lung squamous cell carcinoma to lung adenocarcinoma and promote EMT in NSCLC cells." (PMID 28954633, 2017). "In the current study, we demonstrated that clusterin are up-regulation in lung adenocarcinoma and down-regulation in lung squamous cell carcinoma." (PMID 28954633, 2017). "We found that clusterin was increased in lung adenocarcinoma tissues and decreased in lung squamous cell carcinoma tissues through immunohistochemical technique." (PMID 28954633, 2017). "A previous study reported that clusterin silencing in human lung adenocarcinoma cells induces a mesenchymal-to-epithelial transition." (PMID 28954633, 2017). "One the other hand, CLU was scattered expressed in the cytoplasm of tumor cells and vessel walls in all (12/12) of the lung adenocarcinoma samples although with strong signal." (PMID 29296216, 2017). "We considered serum exosomal proteins ITGAM and CLU as markers for lung adenocarcinoma." (PMID 35291954, 2022). "ITGAM and CLU were identified as serum exosomal protein markers of lung adenocarcinoma." (PMID 35291954, 2022). "MiR-378 could directly target secreted clusterin and help disable the chemoresistance against cisplantin in lung adenocarcinoma cells." (PMID 29088758, 2017). "In cultured lung adenocarcinoma cell lines, clusterin addition could increase SP-C protein expression in 2.75-fold, and decrease p63 protein expression in 0.65-fold (1.54 to 1)." (PMID 28954633, 2017). "The IHC staining of lung adenocarcinoma tissues and nearby tissues was used to detect the expression of ITGAM and CLU." (PMID 35291954, 2022). "Combined with proteomics and bioinformatics predication, we are successful to identify CLSTN1, CLU and NGAL as new candidate biomarkers for lung adenocarcinoma." (PMID 29296216, 2017). "In conclusion, our data suggested that the higher levels of CLSTN1, CLU and NGAL in lung adenocarcinoma cultured medium as well as in serum samples tended to be tumor biomarkers for lung adenocarcinoma diagnosis." (PMID 29296216, 2017). "Combined with two approaches, three proteins including CLSTN1, CLU and NGAL, were highly correlated with lung adenocarcinoma and selected for further analysis." (PMID 29296216, 2017). "Our study demonstrated that clusterin could promote EMT and influence transdifferentiation from lung squamous cell carcinoma to lung adenocarcinoma." (PMID 28954633, 2017). "The data show clusterin were high-expression in lung adenocarcinoma (compare to its adjacent non-cancerous tissues), low-expression in lung squamous cell carcinoma (compare to its adjacent non-cancerous tissues)." (PMID 28954633, 2017).
lung adenocarcinoma (continued). "Additionally, we examined expression levels of CLSTN1, CLU and NGAL of serum samples from 20 patients with lung adenocarcinoma and 10 healthy volunteers with age/sex matched." (PMID 29296216, 2017). "Therefore, our results suggested that CLSTN1, CLU and NGAL showed great potential to be candidate biomarkers for lung adenocarcinoma." (PMID 29296216, 2017).
melanoma (10 papers, 2009 to 2026). A malignant, usually aggressive tumor composed of atypical, neoplastic melanocytes. "Similar observations apply to melanoma cells, ascorbate at a physiological concentration (100 μM) induced apoptosis by inhibiting clusterin expression (CLU)." (PMID 32455696, 2020). "Consistent with previous reports, all three melanoma cell lines, derived from metastatic stages, showed significantly higher level of CLU mRNA (>5 fold) than in FOM-113, healthy melanocytes." (PMID 28623268, 2017). "We first examined CLU expression in healthy melanocyte and three melanoma cell lines available in our lab including A2058, 1205Lu, and C8161." (PMID 28623268, 2017). "The suppression of ascorbate on CLU transcripts was then verified in different melanoma cell lines, and confirmed at the protein level." (PMID 28623268, 2017). "By altering gene expression, this epigenetic action of ascorbate helps decrease melanoma malignancy, exemplified here by CLU downregulation." (PMID 28623268, 2017). "Consistent with previous studies, the level of CLU mRNA is much higher in melanoma cell lines than in healthy melanocytes." (PMID 28623268, 2017). "These separate lines of evidence support the notion that ascorbate induces apoptosis in melanoma cells by suppressing secreted CLU, which further activates Bax and Caspases." (PMID 28623268, 2017). "The suppression of CLU was verified at transcript level in different melanoma cell lines, and at protein level in A2058 cells." (PMID 28623268, 2017). "Furthermore, by establishing a syngeneic melanoma mouse tumor model we found that ubiquitous CLU OE suppressed melanoma cells growth, indicating a likely tumor suppressor function in early phases of tumorigenesis." (PMID 33744871, 2021). "Overall, ubiquitous OE of CLU exerts a tumor suppressive role in the melanoma mouse tumor model." (PMID 33744871, 2021). "Overexpression of clusterin protects melanoma cells from apoptosis." (PMID 32455696, 2020). "In conclusion, ascorbate induces apoptosis in melanoma cells by suppressing CLU expression." (PMID 28623268, 2017). "Five proteins were selected for validation as prognostic factors in 348 melanoma patients and 100 controls by ELISA: serum amyloid A and clusterin; immune system proteins; the cell adhesion molecules plakoglobin and vitronectin and the antimicrobial protein dermcidin." (PMID 27216146, 2016). "Furthermore, grafting melanoma tumor cells in mice increased serum CLU levels in control but also in Tg mice suggesting a possible role of circulating CLU in suppressing tumor promotion in CLU OE Tg mice." (PMID 33744871, 2021). "Moreover, knocking-down CLU might provide a novel way to overcome drug resistance in melanoma." (PMID 32039450, 2020). "Five proteins related to immune and inflammatory responses (SAA, CLU), cell adhesion (PG and VN) and antimicrobial activity (DCD) were selected for validation as prognostic serum biomarkers in a group of 348 melanoma patients using ELISA." (PMID 27216146, 2016). "Significantly higher serum levels of SAA and CLU apolipoproteins were detected in melanoma patients than in healthy controls, although no relation with tumor stage and metastatic progression was evident." (PMID 27216146, 2016). "Whole genome expression analysis uncovered two reactivated TGFβ-responsive genes Clusterin and TGFBI that were more prominent in Aza-sensitive compared to resistant melanoma cells, and their activation enhanced apoptosis as observed by siRNA mediated gene knockdown." (PMID 19234609, 2009).
diabetic nephropathy (9 papers, 2016 to 2025). "Clusterin is also upregulated in the glomeruli of adult patients with kidney disease, including diabetic nephropathy, and it is believed to have a protective role against oxidative stress and to protect podocytes against oxidative stress-induced apoptosis." (PMID 38396489, 2024). "Here, we investigated the role of clusterin in diabetic nephropathy (DN)." (PMID 32913257, 2020).
gastric cancer (9 papers, 2012 to 2024). A primary or metastatic malignant neoplasm involving the stomach. "The low survival rate of gastric cancer is associated with the overexpression of Clusterin protein in gastric CSCs." (PMID 33178014, 2020). "However, in gastric cancer patients, increased CLU expression was associated with poorer OS (p < 0.001), FP (p = 0.013), and PPS (p < 0.001)." (PMID 36685863, 2022). "Nevertheless, overexpression of CLU in gastric cancer biopsies is reported to correlate with lymph node metastasis, tumor invasion, and high tumor stage." (PMID 28902909, 2017). "Combined, our results show that CLU is increased in diffuse SRC adenocarcinomas, and that gastric cancer cells display signal-induced production and secretion of CLU." (PMID 28902909, 2017). "Overall, our results indicate that clusterin is overexpressed in hypergastrinemic rodent models of oxyntic preneoplasia and stimulates gastric cancer cell survival." (PMID 28902909, 2017). "Overexpression of CLU has been identified in different types of cancer such as lung, prostate, and gastric cancers, which correlates with advanced tumor stage, poor prognosis, and resistance to chemotherapies." (PMID 28623268, 2017). "In gastric cancer cell lines, gastrin increased secretion of clusterin, and both gastrin and secretory clusterin promoted survival after starvation- and chemotherapy-induced stress." (PMID 28902909, 2017). "In this study, we investigated the expression and regulation of CLU in oxyntic mucosa of hypergastrinemic rodent models and humans, and elucidated the function of sCLU in gastric cancer cells during stress." (PMID 28902909, 2017). "Next, we performed western blot analysis to show expression of CLU in three human gastric cancer cell lines." (PMID 28902909, 2017). "In the present study, we characterize the expression and regulation of CLU in gastric oxyntic mucosa of hypergastrinemic rodent models and in humans, and elucidate the function of sCLU in human gastric cancer cells during stress." (PMID 28902909, 2017). "In support of this, depletion of CLU, or treatment with verteporfin, an inhibitor of CLU and YAP-signalling, in patient-derived gastric cancer tumorspheres causes apoptosis of gastric cancer stem cells and reduced tumour growth, highlighting the critical pro-survival and oncogenic role of CLU." (PMID 38319453, 2024). "Furthermore, cisplatin and gastrin made gastric cancer cells express and secrete CLU, leading to increased survival and possibly treatment resistance." (PMID 28902909, 2017). "Indeed, immunocytochemistry of gastric cancer cells showed that CLU was mainly located in the perinuclear area and towards the cell membrane, suggestive of secretory pathway localization." (PMID 28902909, 2017). "Given our findings in normal and premalignant rodent mucosa, and since CLU has been found by immunohistochemistry to be expressed in human SPEM and gastric cancer, we did further examinations in human gastric cancer material." (PMID 28902909, 2017). "Both gastrin and CLU might promote cell migration/invasion, and, even though sCLU did not affect migration of AGS-GR cells, our findings do not exclude a pro-migratory role of CLU in other gastric cancer cell lines or in vivo." (PMID 28902909, 2017).
infertile (9 papers, 2015 to 2024). "The results of the discussed studies suggest that glycoproteomic analysis of clusterin may help differentiate the severity of hippocampal atrophy, detect the causes of infertility with an immune background, and monitor the development of cancer." (PMID 36071866, 2022). "This study aimed at checking the associations between the sialylation degree of glycoprotein clusterin (CLU) and levels of oxidative–antioxidant balance markers in infertile men." (PMID 36142505, 2022). "Our aim was to check a clusterin fucosylation profile and degree in seminal plamas and blood sera of infertile men using a modified semi-quantitative lectin-ELISA assay." (PMID 34341430, 2021). "Exposure to emitted radiation from mobile phones was demonstrated to have an up-regulation of both CLU mRNA and its full length protein in infertile semen samples compared with the normozoospermic samples." (PMID 25918601, 2015). "More precisely, the analysis of sperm proteomics showed membrane transport proteins like ANXA proteins and proteins involved in capacitation like CLU protein to be more abundant in infertile groups, while PIP which is also involved in capacitation to be abundant in the fertile population." (PMID 35719135, 2022). "Moreover, we would like to check if there are differences in the profile of fucosylation and fucose expression in clusterin glycoepitopes between groups of examined patients, as well as between seminal plasma and blood serum of infertile men." (PMID 34341430, 2021). "Based on this review, we selected PDIA1, PDIA3, MANF, GRP78, CLU, CRT, and CNX as chaperones for validation as serum-based biomarkers in potentially infertile populations." (PMID 39237030, 2024). "Sperm maturation proteins such as CLU and TPP2 were also reported to be overexpressed in idiopathic infertile men following treatment with antioxidant formulation." (PMID 32155908, 2020). "In the analysis of the results from various GEO databases, it was observed that the mRNA expression levels of the human targets PDIA3, MANF, CLU, CRT, and CNX were decreased in the infertile male group compared to the control group, as reported in the respective data sets." (PMID 39237030, 2024). "The results of ROC curve analysis showed that the determination of seminal plasma parameters: CLU, FUT3, and FUT4 concentrations may be helpful in the differentiation of infertile groups of patients with both normal and abnormal seminal parameters." (PMID 34341430, 2021). "Additionally, although the mRNA levels of the target genes CLU and CNX decrease in the male infertile group compared to the control group, the serum levels of CLU and CNX do not differ between the control and infertile groups." (PMID 39237030, 2024). "ROC curve analysis for examined by us serum parameters revealed that CLU and FUT4 concentrations and relative reactivity of serum CLU glycans with UEA and LCA may be useful in the differentiation of groups of infertile men with abnormal and normal semen parameters." (PMID 34341430, 2021).
type 2 diabetes (9 papers, 2015 to 2025). "Interestingly, patients with pre-existing type 2 diabetes had numerically higher clusterin concentrations (median 59.5 μg/mL in diabetics vs. median 50.8 μg/mL in non-diabetics, p = 0.064)." (PMID 36553017, 2022).
acute kidney injury (8 papers, 2012 to 2024). Sudden and sustained deterioration of the kidney function characterized by decreased glomerular filtration rate, increased serum creatinine or oliguria. "Clusterin expression increases in acute kidney injury, mostly demonstrating anti-apoptotic effects, and is related with lipid utilization, cell aggregation and adhesion." (PMID 36091391, 2022). "Levels of five novel biomarkers, the functional marker serum Cystatin C and the damage markers urinary NGAL, cystatin C, β2-microglobulin and clusterin, were elevated in patients who developed moderate/ severe acute kidney injury." (PMID 34871314, 2021). "Clusterin is a high molecular weight glycoprotein expressed in epithelial cells; in cases of acute renal failure, clusterin is found at high concentrations in the urine, indicating glomerular damage." (PMID 27487916, 2016).